FTO (FTO alpha-ketoglutarate dependent dioxygenase)
Diseases named in the same sentence as FTO in open-access papers (continued):
Sharing a sentence is not in itself a finding about the gene and the disease.
glioblastoma (87 papers, 2017 to 2025). The most malignant astrocytic tumor (WHO grade IV). "FTO has been reported to be downregulated in glioblastoma (GBM) and gastric cancer and its presence is associated with a favorable prognosis in GBM." (PMID 40243425, 2025). "Elevated FTO levels have also been demonstrated in cervical squamous cell carcinoma, colorectal cancer, and glioblastoma." (PMID 40621649, 2025). "In combination with radiotherapy, the downregulation of FTO expression or treatment with the FTO inhibitor FB23-2 combined with radiotherapy significantly inhibits glioblastoma stem cell proliferation and self-renewal and increases apoptosis." (PMID 40986143, 2025). "Conversely, SPI1-induced downregulation of FTO in glioblastoma (GBM) promotes tumor growth by altering the processing of pri-miR-10a in an m6A-dependent manner." (PMID 40271153, 2025). "Likely, FTO has been reported to serve as a key oncogene in glioblastoma, esophageal squamous cell carcinoma, NSCLC, and PDAC." (PMID 38057853, 2023). "Another research found that the specific inhibitor of FTO dramatically suppressed glioblastoma stem cell self-renewal and tumorigenesis." (PMID 37840133, 2023). "In glioblastoma, miR-145 recruited FTO and induced the attachment of FTO and CLIP3 mRNA, and increased intracellular demethylase action, while the translation efficiency of m6A-deficient transcripts was significantly increased." (PMID 38125749, 2023). "The NSAID, meclofenamic acid 2 (MA2) was found to inhibit FTO and thus suppress glioblastoma progression." (PMID 36810281, 2023). "In glioblastoma, a recent study demonstrated the efficacy of another FTO inhibitor, FTO-04, at impairing the proliferation of GSCs whilst preserving neural stem cells." (PMID 37444417, 2023). "Significantly, the oxetane class of FTO inhibitors, FTO-43 demonstrated anti-tumor potency comparable to 5-FU in GC, glioblastoma and AML models." (PMID 36810281, 2023). "Several studies showed that FTO and ALKBH5 (erasers) expression were associated with a less favorable prognosis in patients with glioblastoma (GBM)." (PMID 36281789, 2022). "In glioblastoma, downregulation of FTO or upregulation of METTL3 was involved in the poor prognosis of glioblastoma by promoting the proliferation and self-renewal of glioblastoma stem cells." (PMID 35814454, 2022). "There are currently no consistent data on the oncogenic or tumor suppressor role of FTO in glioblastoma." (PMID 36012529, 2022). "Decreased methyltransferases METTL14 can promote the malignant attribute of glioblastoma stem cells while suppressing the demethylase FTO plays the opposite role." (PMID 36105083, 2022). "For example, lncRNA—just proximal to the X-inactive specific transcript (JPX)—mediated apoptosis in glioblastoma cells in an m6A-dependent manner by promoting FTO/PDK1 interaction." (PMID 36012529, 2022). "Collectively, our findings suggested that the PIKE-A/STAT3/FTO/SDHA axis is a promising target for anti-glioblastoma therapy." (PMID 36232604, 2022). "They show that the use of FTO inhibitor (Meclofenamic acid MA) to target glioblastoma stem cells (GSCs), results in suppressing GSC-induced tumorigenesis as well as increasing the lifespan of GSC-engrafted mice." (PMID 35409166, 2022). "In glioblastoma stem cells, inhibition of FTO suppressed stem cell growth, self-renewal as well as tumor progression." (PMID 34277426, 2021). "The aberrant expression of the FTO showed the enhancing effect on the chemoresistance and glioblastoma stem cell self-renewal." (PMID 34211849, 2021). "For example, in glioblastoma stem cells (GSCs), treatment with the FTO inhibitor MA2 increases m6A levels in GSCs, inhibits GSC growth, and prolongs the lifespan of GSC-transplanted mice." (PMID 33952279, 2021). "For example, in the case of glioblastoma, treatment with an FTO inhibitor was shown to decrease the expression levels of certain oncogenes." (PMID 32375858, 2020).
glioblastoma (continued). "FTO induced Glioblastoma Stem Cells (GSC)growth, self-renewal, tumor progression, and prolonged mouse lifespan by regulating m6A of cancer-associated genes." (PMID 33304380, 2020). "FTO promotes cell growth and self-renewal of human glioblastoma stem cells, and is required for substantial tumor progression." (PMID 29789545, 2018). "An FTO inhibitor suppresses glioblastoma progression and prolongs lifespan of GSC-grafted animals, suggesting that targeting the m6A mRNA methylation machinery is a promising therapeutic tool for glioblastoma." (PMID 28297667, 2017). "The oncogenic role of FTO is not limited to AML; another study showed that inhibition of FTO in glioblastoma stem cells (GSCs) suppresses cell growth, self-renewal, and tumorigenesis." (PMID 29061143, 2017). "In addition, pharmaceutical inhibition of FTO by a chemical inhibitor inhibits tumor progression and significantly prolongs the life of glioblastoma stem cell-transplanted mice." (PMID 38491196, 2024). "Moreover, the FTO inhibitor can regulate the neuronal excitability with anticonvulsant activity,and is responsible for glioblastoma progression." (PMID 36163017, 2022). "Taken together, the present study reveals a novel mechanism by which PIKE-A promotes tumor growth and demonstrates that PIKE-A regulates SDHA expression by promoting the STAT3/FTO axis, thereby promoting mitochondrial function and cell proliferation in glioblastoma." (PMID 36232604, 2022). "Elevated FTO levels are also identified in glioblastoma and cervical squamous cell carcinoma." (PMID 35721711, 2022). "In conclusion, the PIKE-A/STAT3/FTO/SDHA pathway might play a pivotal role in glioblastoma conformation, progression, and proliferation." (PMID 36232604, 2022). "Furthermore, it was shown that FTO knockdown promotes m6A-mediated maturation of miR-10a leading to enhanced glioblastoma progression by targeting 3′-UTR of Myotubularin Related Protein 3 (MTMR3) mRNA and modulation of the Wnt/β-catenin pathway." (PMID 36012529, 2022). "In addition, pharmaceutical inhibition of FTO by a chemical inhibitor suppresses tumor progression and substantially prolongs the lifespan of glioblastoma stem cell-grafted mice." (PMID 35524932, 2022). "Inhibiting FTO in glioblastoma impairs self-renewal and cancer progression." (PMID 33741917, 2021). "For example, a chemical compound, MA2, as an inhibitor of FTO, could effectively suppress the tumor progression of glioblastoma." (PMID 35003212, 2021). "Recently, a study also identified that a new FTO inhibitor, FTO-04, could disrupt glioblastoma stem cells self-renewal, which indicates that FTO-04 may act as a potential treatment for glioblastoma." (PMID 34381710, 2021). "The impact of m6A modification on tumorigenesis in various types of cancer is exposed through deregulation of different components of m6A machinery, such as upregulation of ALKBH5 in glioblastoma stem cells as an indication of poor prognosis, or oncogenic role of FTO in leukemic cell transformation." (PMID 31947544, 2020). "Moreover, the use of MA2 in glioblastoma can effectively inhibit FTO expression and inhibit tumor progression." (PMID 31681576, 2019). "It is also reported that FTO is involved in the progress of glioblastoma development." (PMID 30039919, 2018). "Our finding that the FTO inhibitor MA2 suppresses GSC-initiated brain tumor development suggests that m6A methylation could be a promising target for anti-glioblastoma therapy." (PMID 28297667, 2017). "This significantly enhances the radiosensitivity of glioblastoma stem cells (GSCs), suppresses tumor growth, and prolongs survival, indicating that FTO upregulation promotes GBM radioresistance." (PMID 40823093, 2025). "Thus, Prrc2a “reading” of OLIG2 mRNA (and its demethylation by FTO) might be relevant in the context of glioblastoma too." (PMID 32316617, 2020).
glioblastoma (continued). "Interestingly, FTO deficiency represses tumor progression and increases the lifespan of GSC-grafted mice substantially, suggesting FTO as a potential therapeutic target for glioblastoma." (PMID 30405719, 2018). "In glioblastoma (GBM), pharmacological inhibition of FTO (e.g., using FB23-2) increases m6A modification on the target gene VEGFA, downregulating its expression and impairing DNA damage repair (e.g., sustaining γH2AX foci and reducing Rad51 recruitment)." (PMID 40823093, 2025). "LncRNAs proximal to the X-inactive specific transcript (JPX) decrease the m6A level and increase the stability of phosphoinositide-dependent kinase-1 (PDK1) mRNA by recruiting FTO to PDK1 mRNA, facilitating aerobic glycolysis in glioblastoma multiforme." (PMID 38560499, 2024). "In glioblastoma, the overexpression of m6A methyltransferase METTL3 or METTL14, or correspondingly, the knockdown of FTO inhibited the growth and self-renewal of glioblastoma stem cells." (PMID 39198433, 2024). "In glioblastoma, inhibition of METTL3 and METTL14 expression promotes the development of glioblastoma, and up-regulation of METTL3 or inhibition of FTO expression through MA2 delays tumor growth." (PMID 39033180, 2024). "In this context, inhibitors targeting different RNA modifications, such as FTO or PUS7 inhibitors, have demonstrated promising results in independently suppressing glioblastoma and reducing self-renewal." (PMID 37928731, 2023). "In the context of glioblastoma (GBM), the m6A demethylases FTO and ALKBH5 have also been reported to act as oncogenes." (PMID 32111216, 2020). "FTO levels were also markedly reduced in the most aggressive histological subtype, glioblastoma (GBM), and in patients with wild-type IDH and non-codel 1p/19q status." (PMID 40970086, 2025). "Further, the correlation analysis of AhR and FTO expression in 169 glioblastoma samples revealed that AhR expression was negatively correlated with FTO expression (R = −0.238, p = 0.008), indicating that IDO1 inhibits FTO activity by promoting AhR expression and nuclear translocation." (PMID 39863603, 2025). "In addition, elevated levels were observed for RBM15B, WTAP, FTO, YTHDF2, YTHDF3, IGF2BP2, and IGF2BP3 in glioblastoma samples compared with normal brain controls." (PMID 38398118, 2024). "Besides, lncRNA JPX stabilizes PDK1 mRNA by enhancing FTO-mediated demethylation of PDK1 mRNA, thereby promoting aerobic glycolysis and temozolomide resistance of glioblastoma multiforme cells." (PMID 38560499, 2024). "Decreasing the FTO transcriptional activity may be carried out by transcription factors (TF), for example, SPI1, which is upregulated in glioblastoma cells and has antiapoptotic activity." (PMID 36012529, 2022). "Similarly, lncRNA JPX facilitated aerobic glycolysis through the FTO/PDK1 axis, thus conferring resistance to temozolomide in glioblastoma multiforme (GBM) cells." (PMID 35843942, 2022). "FTO upregulated the MYC level, known as proto-oncogene TF, and downregulated the expression of MAX interactor 1 (MXI1), which binds to the MYC promoter and inhibits its expression, playing an oncosuppressor role in glioblastoma." (PMID 36012529, 2022). "The FTO inhibitor MA2 can inhibit GSC-initiated brain tumor development, suggesting that M6A methylation may be a promising target for anti-glioblastoma therapy." (PMID 33952279, 2021). "However, “erasers” FTO and ALKBH5 have been shown to be more important in glioblastoma, AML, and BRC." (PMID 32547941, 2020). "Utilizing glioblastoma stem cells (GSCs) and xenograft mice, MA2, the ethyl ester form of meclofenamic acid (MA), an FDA-approved non-steroidal anti-inflammatory drug, was identified as a selective inhibitor of FTO that increases m6A mRNA levels and suppresses GSC-initiated tumor progression." (PMID 38071304, 2023).
glioblastoma (continued). "The FTO inhibitor MA2 (an ethyl ester derivative of MA) prolongs the lifespan of GSC-transplanted mice, implying that m6A modification may be a target for inhibiting tumor progression and reversing resistance to radiotherapy and chemotherapy in glioblastoma." (PMID 36118041, 2022). "This study revealed the biological significance of m6A modification in glioblastoma biology, defining the role of m6A modification in GSC self-renewal and tumorigenesis by targeting multiple components of the m6A regulatory machinery, including METTL3, METTL14, and FTO." (PMID 28297667, 2017). "Similarly, the m6A demethylase FTO promotes ferroptosis in nasopharyngeal carcinoma (NPC), but inhibits it in glioblastoma (GBM)." (PMID 40271153, 2025). "In glioblastoma multiforme (GBM), increased levels of the lncRNA that is proximal to X‐inactive (JPX) positively modulate the level of a limiting enzyme of glycolysis, namely PDK1, in an FTO‐dependent manner, thereby contributing to temozolomide chemoresistance." (PMID 38721006, 2024). "Unlike FTO, ALKBH5 has no activity toward m6Am and can be induced under hypoxia conditions in tumors, promoting self-renewal of glioblastoma and breast CSCs." (PMID 39098905, 2024). "FTO was associated with GBM when it was reported that the FDA-approved FTO-inhibitor meclofenamic acid (MA2) suppressed the proliferation of GSCs across five different glioblastoma-derived cell lines, and that MA2 administration in mice suppressed xenograft GBM tumour growth." (PMID 37444417, 2023).
gastric cancer (84 papers, 2018 to 2026). A primary or metastatic malignant neoplasm involving the stomach. "In malignancies such as gastric cancer and breast cancer, upregulation of FTO has been associated with a worse prognosis." (PMID 40243425, 2025). "FTO was overexpressed in gastric cancer tissues and remarkably associated with liver metastasis and poor prognoses." (PMID 40002690, 2025). "Overexpression of FTO is also thought to be associated with increased clonability and survival potential and aggressiveness of gastric cancer cells." (PMID 41145484, 2025). "Increased expression of FTO is significantly linked with poor prognosis of gastric cancer, while its downregulation inhibits the migration, invasion and proliferation of gastric cancer cell lines in vitro." (PMID 38966068, 2024). "We discovered that the two demethylases (ALKBH5 and FTO) showed a little mutation in gastric cancer samples whilst the highest mutation frequency was exhibited by ZC3H13, followed by VIRMA." (PMID 38206646, 2024). "Fat mass and obesity-associated protein (FTO) is the first identified RNA demethylase but little is known about its role in gastric cancer." (PMID 38556586, 2024). "LncRNA AC026691.1 and FTO were intimately associated with the regulation of m6A RNA methyladenine in gastric cancer." (PMID 37365581, 2023). "FTO is an independent prognostic marker for gastric cancer and also the most potent prognostic risk factor among all m6A regulators." (PMID 36918410, 2023). "FTO was considered an independent risk factor for predicting the poor prognosis (HR = 1.60, P = 0.027, 95% CI: 1.10–2.50), with FTO serving as the key prognostic risk factor for OS of gastric cancer patients." (PMID 36561529, 2022). "Previous studies showed that the abnormally high expression of FTO was associated with worse outcomes in cancers, such as gastric cancer, endometrial carcinoma, and lung squamous cell carcinoma." (PMID 33692753, 2021). "In gastric cancer 15, using 3 m6A RNA methylation regulators (FTO, RBM15, ALKBH5), a prognostic risk signature was established." (PMID 33033522, 2020). "According to the evidence, prognostic risk scores showed strong associations with clinicopathological features in gastric cancer, and FTO was correlated with the malignancy of gastric cancer." (PMID 31681576, 2019). "In gastric cancer, FTO silencing reduces the expression of MOXD1, a gene associated with poor prognosis, and may influence cancer‐related pathways." (PMID 41141648, 2025). "The expression of FTO is up-regulated in gastric cancer tissues, which may be associated with the metastasis and progression of gastric cancer." (PMID 38166832, 2024). "However, another study showed that MYC activated in Epstein-Barr virus-associated gastric cancer elevated FTO expression by binding to the FTO promoter." (PMID 39744011, 2024). "In addition, FTO is associated with self-renewal and immune evasion of cancer stem cells, and plays an essential role in the progression and metastasis of gastric cancer." (PMID 36918410, 2023). "Emerging evidence linked FTO with cell migration and invasiveness in vitro in gastric cancer cells." (PMID 36497402, 2022). "In gastric cancer, a risk signature was constructed using 3 m6A RNA methylation regulators (FTO, RBM15, and ALKBH5), which not only was an independent prognostic marker but could also predict the clinicopathological features of gastric cancer." (PMID 33628782, 2021). "FTO might serve as a novel prognostic biomarker for gastric cancer, while the m6A-related risk score might be informative for risk assessment and prognostic stratification." (PMID 32226518, 2020). "Our findings suggest that FTO might serve as a novel prognostic biomarker for gastric cancer, while the m6A-related risk score might be informative for risk assessment and prognostic stratification." (PMID 32226518, 2020).